NF1 (neurofibromin 1)
Diseases named in the same sentence as NF1 in open-access papers (continued):
Sharing a sentence is not in itself a finding about the gene and the disease.
neurofibromatosis (continued). "Optic pathway glioma (OPG) is a rare pediatric low-grade glioma, frequently associated with neurofibromatosis type 1 (NF–1), that presents unique therapeutic challenges due to its anatomical location and its potential to impair vision, endocrine function, and developmental trajectories." (PMID 40867225, 2025). "Furthermore, children with neurofibromatosis type 1 (NF-1) who are at increased risk of pLGG, also have an increased risk of SMN with one study documenting a relative risk of 3.04 of SMN after radiation therapy." (PMID 38912055, 2024). "Neurofibromatosis type 1 (NF1) is a complex system disorder, caused by alterations in RAS pathways." (PMID 38560379, 2023). "Genetic studies have revealed that neurofibromatosis-Noonan syndrome may result from specific NF1 variants, including the p.R1809C variant or in rare instances from co-occurring NF1 and PTPN11 variants." (PMID 36339399, 2022). "Neurofibromatosis results from loss-of-function mutation in NF1 gene on chromosome 17q21." (PMID 35490251, 2022). "Nine children had an underlying syndrome; there were two cases of neurofibromatosis type 1 (NF-1), one Hurler’s syndrome, one Treacher-Collins syndrome, one Williams-Beuren syndrome, two other patients with phacomatoses and two patients with undefined syndromes." (PMID 35792951, 2022). "Neurofibromatosis type 1 (NF1) is caused by inactivating PVs in the NF1 gene." (PMID 37435466, 2022). "All of the variants could reduce mature NF1 protein, leading to neurofibromatosis around the vertebrae, and further scoliosis." (PMID 36061378, 2022). "Our patient had germline NF1 mutation and cutaneous stigmata of neurofibromatosis." (PMID 35490251, 2022). "Germline mutations in the NF1 gene cause Neurofibromatosis type 1 (NF1)." (PMID 34205611, 2021). "Loss-of-function mutation of the NF1 gene is the major genetic cause of neurofibromatosis 110–12." (PMID 34011935, 2021). "Neurofibromatosis type 1 (NF-1) is a rare disease known to cause vascular fragility." (PMID 34239644, 2021). "This can mostly be attributed to the fact that a large proportion of MPNSTs arises in neurofibromatosis patients, an autosomal dominant disease caused by inactivating NF1-mutations, but also to the fact that the unusually large NF1 gene is among the most frequently mutated genes of the human genome." (PMID 33918045, 2021). "Significant progress has been made by the neurofibromatosis research community, including the genetic cause of NF1, the cellular function of the neurofibromin protein, and the identification of cellular components that contribute to the tumours developed in NF1." (PMID 32439933, 2020). "In humans, neurofibromatosis often leads to tumors in peripheral nerves, so we also tested whether loss of nowl or Nf1 affects growth of peripheral nerves in Drosophila to exclude tumor formation in these neurons." (PMID 32339168, 2020). "Somatostatinoma may be sporadic (93.1%) or associated with neurofibromatosis type 1 (NF1), MEN1, and Von Hippel–Lindau syndromes (6.9%)." (PMID 33204258, 2020). "Yang et al27 showed an increased osteoclast activity in neurofibromatosis type 1 mice, and Ghadakzadeh et al28 also reported the hyperactivity of osteoclasts in NF1‐deficient mice, and by inhibiting osteoclast activity with β‐Catenin knockout, enhanced bone repair was achieved." (PMID 32862562, 2020). "The aim of this study was to assess the prevalence and type of congenital heart disease (CHD) and the associated mutation spectrum in a large series of patients with neurofibromatosis type 1 (NF1), and correlate the mutation type with the presence and subgroups of cardiac defects." (PMID 31487937, 2019).
neurofibromatosis (continued). "Another Schwann cell pathology that is of particular interest to the glial research community is Malignant Peripheral Nerve Sheath Tumor (MPNST), a malignant form of Neurofibromatosis Type 1 (NF1) resulting from a loss of function mutation in the Neurofibromin 1 gene." (PMID 31461876, 2019). "Mutations in NF1 may result in juvenile myelomonocytic leukemia, neurofibromatosis, Neurofibromatosis-Noonan syndrome, and Watson syndrome." (PMID 27930734, 2016). "Indeed, another RasGAP encoding gene, the NF1 (neurofibromatosis type 1), is a frequent somatic target for CMMR-D-related cancers and it was also shown to be mutated in murine MLH1-/- embryonic fibroblasts." (PMID 27447752, 2016). "This study suggests that inactivating NF1 mutations outside the context of neurofibromatosis may be the oncogenic mechanism for a subset of sporadic GIST." (PMID 26555092, 2015). "We note that hydroquinone is used cosmetically as a skin-bleaching agent, including by individuals with cafe-au-lait spots (which may be present in individuals with neurofibromatosis who have a mutation in NF1), which could be unadvisable given our findings." (PMID 24386979, 2014). "Germline mutations in the NF1 tumor suppressor gene cause neurofibromatosis type 1 (NF1), a complex genetic disorder with a high predisposition of numerous skeletal dysplasias including short stature, osteoporosis, kyphoscoliosis, and fracture non-union (pseudoarthrosis)." (PMID 21980365, 2011). "Almost 50% of patients in our case series had neurocutaneous manifestations in the form of café-au lait spots and pigmented macules, which might indicate underlying Neurofibromatosis (NF) as the upregulation of RAS in NF-1 may act as a mediator of ES indirectly by upregulation of Tyrosine kinases." (PMID 41522389, 2025). "Approximately 45% present in the context of neurofibromatosis type‐1 (NF‐1), a germline tumour predisposition syndrome (incidence ~1/3,500) caused by constitutional mutations in the tumour suppressor gene neurofibromin 1 (NF1); 45% of cases occur as sporadic tumours and 10% are radiation‐associated." (PMID 32666581, 2020). "Neurofibromatosis encompasses a group of genetic disorders classified as type 1 (NF1), type 2 (NF2), and type 3 (NF3)." (PMID 41515658, 2026). "Neurofibromatosis type 1 (NF1) and NF2 -related Schwannomatosis ( NF2 -SWN) are both inherited syndromes characterized by Schwann cell tumors." (PMID 42125750, 2026). "Neurofibromatosis type 1 (NF1) and NF2-related schwannomatosis (NF2-SWN) are major genetic tumor predisposition syndromes characterized by progressive, often debilitating neoplasms of the peripheral and central nervous systems." (PMID 41898726, 2026). "Notable carcinogens include vinyl chloride and thorium dioxide, while NF-1 (neurofibromatosis), IDH1 (maffucci syndrome), and breast cancer gene (BRCA) 1 and 2 are associated genetic mutations." (PMID 40125238, 2025). "Neurofibromatosis is an autosomal dominant genetic disease with familial inheritance, with neurofibromatosis type 1 (NF-1) being the most common form of neurofibromatosis." (PMID 41170329, 2025). "Associated endocrine disorders include multiple endocrine neoplasia type 2A (MEN2A), von Hippel–Lindau (VHL) disease, neurofibromatosis type 1 (NF1), and Carney Triad." (PMID 40746609, 2025). "Neurofibromatosis: Neurofibromatosis type 1 (NF1)-derived tumours are enriched in blood vessels, with the growth of NF1 tumours being angiogenesis-dependent." (PMID 40649783, 2025). "One case of T-cell acute lymphoblastic leukemia (T-ALL), neurofibromatosis type-1 (NF-1), and testicular carcinoma on bleomycin, etoposide, and cisplatin were observed." (PMID 40710916, 2025).
neurofibromatosis (continued). "Neurofibromatosis type 1 (NF-1) is the most common phakomatosis with an autosomal dominant inheritance pattern." (PMID 41185817, 2025). "In the same way, patients with tuberous sclerosis complex and NF1 are referred to the comprehensive Tuberous Sclerosis and Neurofibromatosis clinics, respectively." (PMID 40351830, 2025). "For example, neurofibromatosis type 1 (NF-1) is known to manifest the ON tortuosity on the MRI images." (PMID 41087679, 2025). "Neurofibromatosis is classified into two subtypes: Neurofibromatosis type 1 (NF1) or peripheral subtype, which affects the vestibular nerve, and Neurofibromatosis type 2 (NF 2), known as central neurofibromatosis." (PMID 41517354, 2025). "Germline mutations such as multiple endocrine neoplasia type 1 (MEN1), von Hippel–Lindau syndrome (VHL), neurofibromatosis type 1 (NF1), and the occasionally tuberous sclerosis complex (TSC) are the most identified PNET-associated mutations." (PMID 38279330, 2024). "Neurofibromatosis was first reported over 140 years ago33, and the NF1 gene product’s function as a Ras GAP was determined 30 years ago34,35." (PMID 38216572, 2024). "Neurofibromatosis type 1 (NF1; MIM#162200) is an uncommon RASopathy caused by mutations in the NF1 tumor-suppressor gene, which predisposes patients to pleiotropic secondary sequelae, including skeletal manifestations." (PMID 38990653, 2024). "RASopathies, which include neurofibromatosis type 1 (NF1), are defined by Ras/mitogen‐activated protein kinase (Ras/MAPK) pathway activation." (PMID 39355740, 2024). "Schwannomatosis is part of the neurofibromatosis spectrum, along with NF1- and NF2-related conditions." (PMID 39062695, 2024). "In the NF1 familial syndrome, patients with neurofibromatosis will present with benign cutaneous neurofibromas and are predisposed to breast, gastric, and pancreatic neuroendocrine tumors." (PMID 38279330, 2024). "Neurofibromatosis encompasses a spectrum of disorders, including two distinct types: NF-1 and neurofibromatosis type 2." (PMID 39364374, 2024). "Neurofibromatosis is a rare genetic and tumor-prone disorder affecting the nervous system, including NF1, NF2, and schwannomatosis." (PMID 39193326, 2024). "Further strengthening the NF1 theory is evidence of other artistic depictions of neurofibromatosis from the Hellenistic era - researchers have identified statues with “multiple skin nodules on the torso and limbs consistent with Neurofibromatosis”." (PMID 37908901, 2023). "No patients had a familial Moyamoya history, while 2 patients of the MMS group and 4 of the NF1 group had familial forms of Neurofibromatosis." (PMID 36980803, 2023). "Further, the NF1 protein is found in various brain regions and plays a key role in neurofibromatosis." (PMID 37709831, 2023). "Neurofibromatosis type 1 (NF-1) results from a mutant form of the NF1 gene, which is inherited as an autosomal dominant trait." (PMID 38021712, 2023). "Although it shares its name with NF1, neurofibromatosis type 2 (NF2) is a completely different clinical entity." (PMID 38139220, 2023). "Based on these observations, we conclude that a non-toxic, targeted approach to Alk inhibition is the best strategy for developing effective treatments for neurofibromatosis, Nf1." (PMID 37760547, 2023). "Based on clinical information (tumor types, café au lait spots), patients #12 and #13 were diagnosed with neurofibromatosis type 1 (NF1) and type 2 (NF2), respectively." (PMID 38139220, 2023). "Neurofibromatosis (NF; NF1, NF2) is a genetic, neurocutaneous disorder characterized by nerve sheath tumors of the central and peripheral nervous system, including the brain, spinal cord, and skin." (PMID 38127915, 2023). "Of those, 1902 had neurofibromatosis (including 1783 NF1), 444 TSC, 63 von Hippel-Lindau disease, and 39 had ataxia-telangiectasia (median [IQR] follow-up among children with neurocutaneous syndromes, 19.9 [10.7-20] years)." (PMID 37490289, 2023).
neurofibromatosis (continued). "Neurofibromatosis type 1 (NF-1) is an autosomal-dominant genetic disorder with nearly 100% penetrance." (PMID 35490251, 2022). "STX3451 has been previously shown to be cytotoxic to cell lines of the rare neurofibromatosis NF1 and NF2 tumors." (PMID 35744942, 2022). "Neurofibromatosis type 1 (NF1; MIM 1622009), one of the most frequent genetic diseases, is caused by heterozygous mutations of the NF1 tumor suppressor gene, and is characterized by highly variable expressivity." (PMID 36612057, 2022). "Neurofibromatosis type 1 (NF1) is a common human genetic disease with age-dependent phenotype progression." (PMID 35093157, 2022). "A synchronous case of small bowel adenocarcinoma(SAB) is reported, accompanied with gastrointestinal stromal tumor(GIST),and gangliocytomain in an elderly woman with neurofibromatosis type 1 (NF-1)." (PMID 36620543, 2022). "Neurofibromatosis type 1 (NF-1) is an autosomal dominant disorder that affects approximately 1 in 3,000 individuals globally." (PMID 35515133, 2022). "Neurofibromatosis type 2 (NF2, also known as central neurofibromatosis) is an autosomal dominant disorder that is distinct from NF1 on both genetic and clinical grounds." (PMID 35320498, 2022). "OPG is believed to be the most prevalent intracranial tumor in patients with neurofibromatosis type 1 (NF-1) and can occur in 15–20% of NF-1 cases." (PMID 36230704, 2022). "Mendelian disorders occurred more than once include Osteogenesis Imperfecta Type I (COL1A1, MIM:166200), Neurofibromatosis, Type I (NF1, MIM:162200) and Marfan Syndrome (FBN1, MIM:154700)." (PMID 35346302, 2022). "The purpose of this review is to shed light on the correlation between neurofibromatosis and reported malignancies, with a focus on NF1 and its characteristically defective protein neurofibromin, as well as establish potential directions of research." (PMID 35053664, 2022). "NF-1 (von Recklinghausen’s disease) which is known as the most common form of neurofibromatosis with an incidence of 1 per 3000–4000 people worldwide, is associated with numerous clinical manifestations." (PMID 34814912, 2021). "Neurofibromatosis (NF) is an auto somal dominant hereditary disorder that consists of two subtypes: NF-1 and NF-2." (PMID 34814912, 2021). "Neurofibromatosis (NF) is an autosomal genetic disorder with three types, including NF1, NF2, and schwannomatosis." (PMID 34430126, 2021). "The transition between closed, self-inhibited states of Nf1 and open states provides guidance for targeted studies deciphering the complex molecular mechanism behind the widespread neurofibromatosis syndrome and Nf1 dysfunction in carcinogenesis." (PMID 34707296, 2021). "The neurofibromatosis syndromes, including NF1, NF2, and schwannomatosis, are tumor suppressor syndromes characterized by multiple nervous system tumors, particularly Schwann cell neoplasms." (PMID 34604034, 2021). "According to the classification of the National Institute of Health (NIH) in 1988, neurofibromatosis comprises neurofibromatosis type 1 (NF1) and type 2 (NF2)." (PMID 33691671, 2021). "As most reported cases of choroidal ganglioneuroma showed a medical history of NF-1, genetic changes in neurofibromatosis-related genes were evaluated for all subjects." (PMID 33308182, 2020). "Nf1 is another important regulator of Ras signaling, and mutations in Nf1 and LZTR1 both give rise to types of neurofibromatosis." (PMID 32339168, 2020). "Numerous central nervous system (CNS) manifestations have been identified in NF-1 including optic pathway gliomas (OPGs), optic nerve tortuosity, cerebral astrocytomas, hydrocephalus, and neurofibromatosis bright objects (NBOs) on imaging." (PMID 31655505, 2019).
neurofibromatosis (continued). "Neurofibromatosis type 1 (NF-1) is an autosomal dominant neurocutaneous disorder characterized by multiple neurofibromas, cutaneous pigmentation, and skeletal dysplasia." (PMID 31655505, 2019). "A neurofibromatosis-Noonan Syndrome (MIM 601321) was reported and linked to variants in NF 1, but also to the co-occurrence of independent variants in NF1 and PTPN11 in the same patient." (PMID 31370276, 2019). "Another autistic condition, neurofibromatosis type 1 (NF1), is an autosomal dominant neurodevelopmental disorder, mainly caused by mutations in gene NF1." (PMID 28579943, 2017). "Neurofibromatosis type 1 (NF1; MIM# 162200) is a familial cancer syndrome that affects 1 in 3,500 individuals worldwide and is inherited in an autosomal dominant fashion." (PMID 28454108, 2017). "Neurofibromatosis type 1 (NF-1) is an autosomal dominant disorder characterized by cafe au lait macules and neurofibromatosis." (PMID 29382000, 2017). "Impaired motor learning was reported in several ASD mouse models such as GABRB3, Ube3a (Angelman's syndrome) and NF1 (Neurofibromatosis type 1) mice." (PMID 26973485, 2016). "Neurofibromatosis is due to germline mutations in neurofibromin 1, a RAS-GAP protein and negative regulator for RAS signaling, and germline NF1 mutations accompanied by somatic events have been identified in NF1 GIST cases." (PMID 26555092, 2015). "Neurofibromatosis type I (NF1, MIM#162200) is a relatively frequent genetic condition, which predisposes to tumor formation." (PMID 25775093, 2015). "Similar features are shown for NF1, a gene on chromosome 17 that mediates the autosomal dominant disease, neurofibromatosis." (PMID 25350658, 2014). "We describe a case in which tandem duplications in NF1 gene were detected in a neurofibromatosis patient who presented a personal and familial history of compatible with a hereditary cancer syndrome, specially lymphoproliferative malignancies." (PMID 25580325, 2014). "Large deletions encompassing the NF1 gene region at 17q11.2 are present in 5 to 10% of patients with neurofibromatosis type 1 (NF1; MIM #162200)." (PMID 24958239, 2014). "The company report also flagged rare heterozygous variants in NF1 and TRPS1, which would, if truly present and functional, cause autosomal dominant disorders (neurofibromatosis (OMIM #162200) and trichorhinophalangeal syndrome (OMIM # 190350), respectively)." (PMID 24954083, 2014). "For instance, “NF1” can refer to a disease (“Neurofibromatosis Type 1”) or to a protein (“Neurofibromin 1”)." (PMID 24063607, 2013). "Mutations in tuberous sclerosis complex (TSC) 1/TSC2, neurofibromatosis 1 (NF1), and Phosphatase and tensin homolog (PTEN) lead to syndromic ASD with tuberous sclerosis, neurofibromatosis, or macrocephaly, respectively." (PMID 23533374, 2013). "Neurofibromatosis type 1 (NF1) is a good model in this respect, because it is a monogenic disorder caused by mutations in the NF1 gene." (PMID 23406822, 2013). "Four patients had neurofibromatosis-1 (NF1); four tumors had heterologous rhabdomyoblastic differentiation (malignant triton tumor)." (PMID 24133387, 2013). "Neurofibromatosis type 1 (NF1) (MIM #162200) is a common familial cancer syndrome with a prevalence of 1 in 2,500 and an autosomal dominant inheritance pattern; it is fully penetrant by 5 years of age." (PMID 23244495, 2012). "Neurofibromatosis-1 (NF-1) is a relatively common autosomal dominant disease characterized by multiple cutaneous fibromatoses and café au lait spots." (PMID 21731277, 2011). "Familial predisposition is seen mainly in patients with multiple endocrine neoplasia type 2, neurofibromatosis Type 1 (NF-1), von Hippel-Lindau disease and familial carotid body tumors." (PMID 20219130, 2010).